DRD1 (dopamine receptor D1)
Description:
Dopamine receptor whose activity is mediated by G proteins which activate adenylyl cyclase. Forms heterotetramers with DRD3 to potentiate beta-arrestin recruitment and mediate locomotor activity.
Synonyms: D1R; DADR; DRD1A
Tractability: Small molecule: an approved drug acts on it; a structure with a bound ligand is known; a high-quality ligand is known; it belongs to a druggable protein family. Antibody: its Gene Ontology location is reachable by antibodies, with high confidence; UniProt places it where antibodies can reach, with medium confidence; UniProt predicts a signal peptide or a membrane-spanning region; the Human Protein Atlas places it where antibodies can reach. PROTAC: ubiquitination databases record sites on it; a small molecule that binds it is known. Other modalities: an approved drug acts on it.
Target class: Small molecule receptor (family A GPCR); Dopamine receptor; Family A G protein-coupled receptor; Monoamine receptor; Membrane receptor
Safety:
Unwanted effects reported when the protein is acted on. In parentheses: how it was acted on, where the effect was seen, and who reports it.
anxiety (Lynch et al. (2017): inhibition, acute dosing, renal, central nervous system, cardiovascular; Bowes et al. (2012): inhibition, cardiovascular system, central nervous system)
decreased blood pressure (Bowes et al. (2012): activation, cardiovascular system, central nervous system; Lynch et al. (2017): activation, acute dosing, renal, central nervous system, cardiovascular)
depression (Bowes et al. (2012): inhibition, cardiovascular system, central nervous system; Lynch et al. (2017): inhibition, acute dosing, renal, central nervous system, cardiovascular)
dizziness (Lynch et al. (2017): activation, acute dosing, renal, central nervous system, cardiovascular; Bowes et al. (2012): activation, cardiovascular system, central nervous system)
dyskinesia (Bowes et al. (2012): inhibition, cardiovascular system, central nervous system; Lynch et al. (2017): inhibition, acute dosing and activation, acute dosing, renal, central nervous system, cardiovascular)
nausea (Lynch et al. (2017): activation, acute dosing, renal, central nervous system, cardiovascular; Bowes et al. (2012): activation, cardiovascular system, central nervous system)
suicidal intent (Lynch et al. (2017): inhibition, acute dosing, renal, central nervous system, cardiovascular; Bowes et al. (2012): inhibition, cardiovascular system, central nervous system)
abuse potential (activation; cardiovascular system, central nervous system; source: Bowes et al. (2012))
anti-emetic effects (inhibition; cardiovascular system, central nervous system; source: Bowes et al. (2012))
catalepsy (inhibition, acute dosing; renal, central nervous system, cardiovascular; source: Lynch et al. (2017))
convulsions (activation, acute dosing; renal, central nervous system, cardiovascular; source: Lynch et al. (2017))
decreased convulsions (inhibition, acute dosing; renal, central nervous system, cardiovascular; source: Lynch et al. (2017))
decreased locomotor activity (inhibition, acute dosing; renal, central nervous system, cardiovascular; source: Lynch et al. (2017))
drug abuse/dependence (activation, acute dosing; renal, central nervous system, cardiovascular; source: Lynch et al. (2017))
fibrotic valvular heart disease (activation, chronic dosing; renal, central nervous system, cardiovascular; source: Lynch et al. (2017))
headache (activation, acute dosing; renal, central nervous system, cardiovascular; source: Lynch et al. (2017))
headaches (activation; cardiovascular system, central nervous system; source: Bowes et al. (2012))
heart failure (activation, chronic dosing; renal, central nervous system, cardiovascular; source: Lynch et al. (2017))
increased arousal (activation, acute dosing; renal, central nervous system, cardiovascular; source: Lynch et al. (2017))
increased blood pressure (inhibition, acute dosing; renal, central nervous system, cardiovascular; source: Lynch et al. (2017))
increased urinary sodium excretion (activation, acute dosing; renal, central nervous system, cardiovascular; source: Lynch et al. (2017))
increased urine excretion (activation, acute dosing; renal, central nervous system, cardiovascular; source: Lynch et al. (2017))
increased/decreased locomotor activity (activation, acute dosing; renal, central nervous system, cardiovascular; source: Lynch et al. (2017))
natriuresis (activation; cardiovascular system, central nervous system; source: Bowes et al. (2012))
neurodegeneration (activation, acute dosing; renal, central nervous system, cardiovascular; source: Lynch et al. (2017))
parkinsonian symptoms (tremors) (inhibition; cardiovascular system, central nervous system; source: Bowes et al. (2012))
parkinsonism (inhibition, acute dosing; renal, central nervous system, cardiovascular; source: Lynch et al. (2017))
psychosis (activation, acute dosing; renal, central nervous system, cardiovascular; source: Lynch et al. (2017))
vascular relaxation (activation; cardiovascular system, central nervous system; source: Bowes et al. (2012))
social withdrawal or nausea (source: ClinPGx)
Gene: Protein-coding gene on chromosome 5 (175,440,027 to 175,444,794, reverse strand). Ensembl gene ENSG00000184845.
Subcellular location: Cell membrane; Endoplasmic reticulum membrane; Cell projection, cilium membrane; Cell projection, dendrite; Cell projection, dendritic spine
Subcellular location (Human Protein Atlas): Plasma membrane; Cytosol
Pathways (Reactome):
Signal Transduction: Dopamine receptors; G alpha (s) signalling events
Gene Ontology:
Molecular function: arrestin family protein binding; dopamine binding; dopamine neurotransmitter receptor activity; dopamine neurotransmitter receptor activity, coupled via Gs; G-protein alpha-subunit binding; heterotrimeric G-protein binding; protein binding; G protein-coupled receptor activity
Biological process: adenylate cyclase-activating dopamine receptor signaling pathway; adenylate cyclase-activating G protein-coupled receptor signaling pathway; cellular response to catecholamine stimulus; G protein-coupled receptor signaling pathway, coupled to cyclic nucleotide second messenger; phospholipase C-activating dopamine receptor signaling pathway; positive regulation of release of sequestered calcium ion into cytosol; adenylate cyclase-activating adrenergic receptor signaling pathway; adult walking behavior; cerebral cortex GABAergic interneuron migration; dopamine metabolic process; G protein-coupled dopamine receptor signaling pathway; learning; mating behavior; memory; phospholipase C-activating G protein-coupled receptor signaling pathway; positive regulation of cell migration; positive regulation of MAPK cascade; positive regulation of potassium ion transport; positive regulation of synaptic transmission, glutamatergic; regulation of dopamine uptake involved in synaptic transmission; regulation of synaptic plasticity; response to xenobiotic stimulus; synapse assembly; transmission of nerve impulse; visual learning; and 8 more
Cellular component: ciliary membrane; cilium; G protein-coupled receptor complex; non-motile cilium; plasma membrane; postsynaptic membrane; dendritic spine; endoplasmic reticulum membrane; 9+0 non-motile cilium; dendrite; endomembrane system; endoplasmic reticulum; GABA-ergic synapse; glutamatergic synapse; membrane; nucleus; presynaptic membrane
Genetic constraint (gnomAD): Loss-of-function variants: 2 observed, 24.99 expected, observed/expected ratio (o/e) 0.08, 90% interval 0.032 to 0.25. The upper end of that interval is the gene's LOEUF score, 0.25, which puts it in group 1 of 6, group 1 being the genes least tolerant of losing a copy. Missense variants: 376 observed, 589.17 expected, observed/expected ratio (o/e) 0.64, 90% interval 0.59 to 0.69. Synonymous variants: 218 observed, 237.97 expected, observed/expected ratio (o/e) 0.92, 90% interval 0.82 to 1.02.
Homologues: Orthologues: chimpanzee DRD1 (100% identical), macaque DRD1 (99% identical), dog DRD1 (96% identical), pig DRD1 (95% identical), rabbit DRD1 (93% identical), guinea pig DRD1 (92% identical), mouse Drd1 (91% identical), rat Drd1 (91% identical), tropical clawed frog drd1 (81% identical), zebrafish drd1b (72% identical). Paralogues in human: DRD5 (56% identical), HTR4 (28% identical), HTR1A (27% identical), HTR1D (26% identical), HRH2 (25% identical), DRD3 (24% identical), DRD4 (24% identical), TAAR1 (23% identical), CHRM3 (23% identical), CHRM5 (23% identical), CHRM2 (22% identical), CHRM4 (22% identical), and 13 more.
Diseases named in the same sentence as DRD1 in open-access papers:
DRD1 is named in the same sentence as 178 diseases in open-access papers, as found by Europe PMC text mining. Sharing a sentence is not in itself a finding about the gene and the disease. The quoted sentences say what the papers report.
schizophrenia (65 papers, 2012 to 2025). A major psychotic disorder characterized by abnormalities in the perception or expression of reality. "OLZ treatment in rats affected the 5mC levels of several genes associated with schizophrenia, including dopamine D1 receptor (DRD1), dopamine D2 receptor (DRD2), dopamine D5 receptor (DRD5), and others." (PMID 38203806, 2024). "In the structure of the dopamine receptor D1 (localized on the postsynaptic membrane), two single nucleotide polymorphisms associated with the risk of developing schizophrenia have been identified: G198A and G1263A." (PMID 30967134, 2019). "Risk variants of rs5326 have been associated with a decreased DRD1 expression, a reduced cognitive functioning in both healthy males and bipolar patients, and an increased risk of neuropsychiatric disorders, such as schizophrenia and heroin addiction." (PMID 29541058, 2018). "Network 1 included, as well as Npy and Bdnf, several transcripts involved in neurotransmission and implicated in schizophrenia, such as dopamine D1 and D4 receptors (Drd1 and Drd4)." (PMID 30348978, 2018). "The DRD1 rs4532 allele has been associated with fMRI measures of working memory tied to prefrontal activation and illnesses like schizophrenia." (PMID 29634738, 2018). "This SNP may also be important to DRD1 as it has been associated with dopamine-associated conditions including tardive dyskinesia in schizophrenia, attention deficit hyperactivity disorder (ADHD), and response to stimulant medications in ADHD." (PMID 29634738, 2018). "Therefore, it is possible that, in males, the combination of higher DRD1 expression and higher dopamine turnover in the prefrontal cortex may be a risk factor for schizophrenia." (PMID 39595853, 2024). "Biological pathways have been proposed and pursued, centering on the schizophrenia-linked candidate neurotransmitter dopamine; in rodents, infection with T. gondii leads to aberrant dopamine signaling and reduced expression of genes within the dopamine pathway, such as DRD1, DRD5 and MAOA." (PMID 26886853, 2016). "The affected dopamine receptor D1 and decreased dopamine levels are found in patients with schizophrenia." (PMID 36613008, 2022). "This profile of the Drd1 mutant rat offers the field of neuroscience a novel genetic rat model to study a series of psychiatric disorders including schizophrenia, autism, depression, bipolar disorder and drug addiction." (PMID 27483345, 2016). "Of particular interest, the Srrm2+/− and Dagla+/− mutants had a significant (FDR < 0.05) upregulation of the “response to dopamine” gene set in the striatum, including increased expression of Drd1 and Drd2, which are dopamine receptors highly relevant to schizophrenia." (PMID 41022686, 2025). "Although a link between elevated Drd2 expression and schizophrenia-like behavioral abnormalities has been suggested, it remains to be seen whether there is a link between the other dopamine receptor Drd1 and behavior." (PMID 38336912, 2024). "DRD1, DRD2, and HTR2A have been implicated as drug targets in schizophrenia." (PMID 36671883, 2022). "The level of DRD1 in schizophrenia was less than in the control in GSE25673 (p < 0.001)." (PMID 35062349, 2022). "Other studies have revealed that altered expression of DRD1, which was downregulated in the present study, may contribute to the pathophysiology of schizophrenia and affective disorders." (PMID 35012632, 2022). "In this work, we analyzed 28 studies conducted from 1989 to 2021, studying 37 genetic variations, including SNVs/polymorphisms of four candidate dopamine receptor genes (DRD1, DRD2, DRD3, DRD4) involved in the development of AIP and AITD in patients with schizophrenia." (PMID 34440083, 2021). "Therefore, in order to investigate the role of Drd1 in social cognition as a transdiagnostic marker for schizophrenia and comorbid psychiatric disorders, we introduce in the present paper a novel rat model with a mutation in the Drd1 gene." (PMID 27483345, 2016).
schizophrenia (continued). "Of the remaining 16 involved_in associations involving DRD1 three of the diseases represent known off-label indications for Propranolol being: Bipolar disorders; Schizophrenia, Alcoholism and as a non-stimulant treatment for ADHD (Gobbo & Louzã, 2014)." (PMID 26844016, 2016). "Indeed, rescue of MK-801-induced vigilance deficits and PCP-induced disinhibition by a dopamine D1 receptor (DRD1) agonist aligns with previous evidence that such treatment may enhance cognition in schizophrenia." (PMID 36408755, 2022). "Identifying the cellular localization of this up-regulation of DRD2 would be important for determining whether the increased DRD2 is perhaps counteracting DRD1 effects on pyramidal neurons or bolstering the inhibitory drive of interneurons in schizophrenia prefrontal cortex." (PMID 23720610, 2013). "Moreover, we propose that two major pro-cognitive targets for schizophrenia, the dopamine D1 receptor (DRD1) and the alpha 7 nicotinic acetylcholine receptor (nAChR), may be ideal for augmenting reward-based learning in CR." (PMID 23785309, 2013). "However, given the timing of late developmental up-regulation and the putative working model of an immature cortex found in schizophrenia, one may predict that DRD1 should be decreased in schizophrenia." (PMID 23720610, 2013). "Here we examined the relative expression of DRD1, DRD2 and IDO1 and IDO2 genes transcription in MK-801 model schizophrenia group and T. gondii infected rat brain and subsequent neurotransmitter changes." (PMID 36950587, 2023). "In conclusion, the DRD1, DRD2, and GSK3 were expressed differentially between the schizophrenia patients and the healthy controls." (PMID 35062349, 2022). "In addition, a recent meta-analysis was performed that was based on over 1000 association studies on schizophrenia, and this study highlighted 16 genes, which were mostly dopamine-related, including catechol-O-methyltransferase (COMT) and dopamine receptors D1, D2, and D4 (DRD1, DRD2 and DRD4)." (PMID 24086483, 2013). "A recent study reports that the level of N-methyl-D-aspartate (NMDA) glutamate receptor, dopamine receptors (DRD1-4), and HTR3 may potentially serve as peripheral biomarkers for schizophrenia." (PMID 37990254, 2023). "DRD1 was detected and showed no alteration between the schizophrenia and the healthy controls (p > 0.05)." (PMID 35062349, 2022). "Alteration in Drd1 expression may account for the absence of memory impairment and depressive symptoms in our G × E model mice, as observed in other models of schizophrenia." (PMID 38336912, 2024).
Parkinson disease (49 papers, 2012 to 2026). A progressive degenerative disorder of the central nervous system characterized by loss of dopamine producing neurons in the substantia nigra and the presence of Lewy bodies in the substantia nigra and locus coeruleus. "Highlighting cross-expression’s biological utility, our network shows that genes Drd1 and Gpr6, which are individually implicated in Parkinson’s disease (PD), are cross-expressed within the striatum, hinting at their joint role in PD pathophysiology." (PMID 41163012, 2025). "We focused on Drd1 and Gpr6, which are implicated in Parkinson’s disease (PD) due to their hypo- and hyperactivity, respectively." (PMID 41163012, 2025). "This process is inherently dependent on the researchers’ interests, so we focused on Drd1 and Gpr6, which are implicated in Parkinson’s disease (PD) due to their hypo- and hyperactivity, respectively." (PMID 39345494, 2025). "We report a patient with classical infantile parkinsonism-dystonia in whom we identified a homozygous variant in DRD1 resulting in loss-of-function of the D1 receptor, as demonstrated through an in vitro overexpression HEK-293T cell system." (PMID 37048120, 2023). "Hyperexcitability of DRD1 neurons is thought to underlie the dyskinetic response to L-DOPA treatment in animal models of Parkinson’s Disease." (PMID 23967330, 2013). "DRD1 agonists such as Levodopa are frequently administered to the patients with Parkinson’s disease, who generally present lower bone mineral density." (PMID 28374823, 2017). "DRD1 activation improves adult hippocampal neurogenesis and exerts anxiolytic and antidepressant‐like effect via activation of Wnt/beta‐catenin pathways in rat model of Parkinson’s disease." (PMID 35262262, 2022). "Concurrently, matrix Drd2-SPN and Drd1-SPN dysfunction may disrupt indirect and direct pathways, and together with dopamine fluctuations, these circuit-level changes could underlie the emergence of parkinsonism and chorea." (PMID 40943492, 2025). "Dopaminergic neurotransmission plays a crucial role in motor function through the coordination of dopamine receptor (DRD) subtypes, such as DRD1 and DRD2, thus the functional imbalance of these receptors can lead to Parkinson's disease." (PMID 39562043, 2025). "Some of the players in the outlined route like ADAM17, CX3CL1, DRD1, GRIA1, and LCAM1 have been claimed in animal model studies as therapeutic targets for Parkinson's disease." (PMID 24688734, 2013). "Of note, in the healthy human substantia nigra, DRD1, DRD3, DRD4, and DRD5 did not exhibit an expression pattern opposite to that of the Parkinson's disease‐associated molecule SNCA." (PMID 41249856, 2025). "In contrast to rasagiline’s efficacy in Parkinson disease, this was independent of existing variances in the MAOB and DRD1 genes." (PMID 38474416, 2024).